IL13 (interleukin 13)
Diseases named in the same sentence as IL13 in open-access papers (continued):
Sharing a sentence is not in itself a finding about the gene and the disease.
autoimmune disease (continued). "In addition to allergic responses, basophils are critically involved in autoimmune diseases, cancer, tissue repair, and fibrosis by releasing cytokines such as IL-4 and IL-13 that can modulate Th2 and M2-type immune responses." (PMID 36613520, 2022). "IL13, which is synthesized by Th2 cells, NKT-cells and other immune cells, also plays a role in the development and maintenance of inflammation, and is associated with autoimmune diseases in both mice and humans." (PMID 33579033, 2021). "Th 1 cytokines, such as TNF-α and IFN-γ, are known to lead the progression of autoimmune diseases such as type 1 diabetes and multiple sclerosis (MS), while IL-4, IL-10, and IL-13 refer to Th 2 cytokines and inhibit the pro-inflammatory response and reduce damage." (PMID 34445510, 2021). "Interestingly though, the enriched target genes showed co-expression in the mature CD19+ B cell subset and some of them (IL-6, IL-13, PRDM1 and TLR4) have been reported to be associated genetically with autoimmune diseases." (PMID 33897713, 2021). "While IL-17 is a strong proinflammatory cytokine associated with host defense against bacterial and fungal infections and is also elevated in several autoimmune diseases, IL-5/IL-13 and Arg1-positive M2 macrophages are part of the anti-inflammatory type 2 (Th2) immunity." (PMID 28680858, 2017). "Since the range of immunologic effects of IL13 may not overlap completely with those of IL-4, it will be critical to determine the potential benefit provided by responses biased toward IL-13 production in the context of autoimmune disease." (PMID 21179412, 2010). "IL-13 was significantly upregulated in C.acnes “low” MC1 patients, a cytokine also found to be increased in the serum of patients with (Th2-mediated) autoimmune diseases like systemic lupus erythematosus and systemic sclerosis." (PMID 38322145, 2024). "Firstly, we detected IL-2, IL-4, IL-5, IL-13, IL-17A, IL-17F, IL-22, IFN-γ, and TNF-α in the plasma to exclude the influence of infection or autoimmune disorders, and the standard curves were verified." (PMID 38343544, 2024). "Interleukin-4 (IL4) and Interleukin-13 (IL13) are anti-inflammatory cytokines and are considered as important mediators in pathology of the autoimmune diseases." (PMID 37090926, 2023). "The role of IL-13 in the pathogenesis of autoimmune disorders is still not fully understood, but a role in T-helper cell dysregulation is suggested." (PMID 38322145, 2024). "In addition, recent studies have reported the potential roles of IL-6R, IL-13, and CCL11/Eotaxin in autoimmune diseases such as primary Sjögren’s syndrome through T and B helper cells." (PMID 36187125, 2022). "It has been reported that α-GalCer stimulation can induce iNKT cells to produce both anti-inflammatory cytokines (e.g., IL4, IL13, and IL10) and pro-inflammatory cytokines (e.g., IFNγ, TNFα, and IL17), ultimately determining the outcome of autoimmune diseases such as EAE." (PMID 30766446, 2019). "Although the role of IL13 is not clear, variations in the IL13 gene result in deregulation of the Th1 and Th17 pathways in related autoimmune diseases such as psoriatic arthritis." (PMID 26861312, 2016). "While autoimmune diseases, including MS, are more common in women, the incidence and severity of EAE in mice, null for IL-13, was lower in females compared to males, suggesting the possibility that the contribution of IL-13 to EAE/MS may be gender specific." (PMID 27304970, 2016). "Therefore, in assessing patients with autoimmune disorders, the measurement of Th1 (IFN-γ), Th2 (IL-4, IL-5, IL-13) and Th17 (IL-17) cytokine production by cultured lymphocytes will guide CAM practitioners in tailoring proper treatments for Th1- and Th17-mediated autoimmune diseases." (PMID 19622600, 2011).
dermatitis (49 papers, 2009 to 2025). An inflammatory process affecting the skin. "Animal studies have shown that DEP exposure elevates Th2-type cytokines IL-4 and IL-13, changes associated with AD-like skin inflammation." (PMID 40115349, 2025). "AD is a skin disorder with both compromised skin barrier function and persistent itching symptoms, which is associated with elevated levels of IL-4 and IL-13." (PMID 37978564, 2023). "AD appears to be characterized by skin inflammation, barrier dysfunction, and chronic pruritus, which are all attributable to excessive activation of the IL-13/IL-4‒JAK‒STAT6/STAT3 axis and its associated immune reaction." (PMID 33233866, 2020). "Moreover, p63 can help prevent particular dermatitis brought on by suppression of type 2 cytokines (interleukin 4 [IL-4] and IL-13) linked to keratinocyte development." (PMID 38584846, 2024). "FC alleviated AD apparent symptoms, such as dermatitis score, transepidermal water loss, epidermal thickness, and mast cell infiltration upon declining pro-inflammatory cytokines and mediators, IL-6, IL-5, IL-13, TSLP, and TNF-α." (PMID 37689763, 2023). "The scratch signal exacerbates skin inflammation and conversely upregulates IL-13Rα2 expression, which may suppress excess IL-13 activity caused by the decoy function of IL-13Rα2 in keratinocytes." (PMID 31284553, 2019). "Subcutaneous injection of OVA into the sole of the paw causes skin inflammation, with increased levels of interleukins (IL-1beta, IL6, IL13), cytokines (TNF-alpha), and chemokines (CCL11) in the skin of this region." (PMID 40095628, 2025). "IL-25 as another important alarmins to activate ILC2s has been suggested to play an essential role in driving IL-13 expression by skin ILC2s to mediate skin inflammation in mouse AD model, both in acute and chronic phase." (PMID 40236701, 2025). "The results showed that CBG improved dermatitis severity score, epidermal thickness, and mast cell count and reduced inflammatory cytokines (Tslp, Il1b, Il4, Il6, Il13, Il17, Il18, Il22, and Il33) by qRT-PCR (p < 0.001)." (PMID 39851511, 2025). "In this section, we will focus on the roles of ILC2s in AD which mediated the skin inflammation by producing T2 cytokines such as IL-5 and IL-13." (PMID 40236701, 2025). "In Dfb-induced AD mice, UFB shower treatment improved the dermatitis score, downregulated the gene expression of AD-related inflammatory cytokines (IL-4 and IL-13), and upregulated skin barrier-related molecules." (PMID 39790997, 2024). "Dupilumab, a human monoclonal antibody against IL-4 receptor alpha, blocks signaling of IL-4 and IL-13, improving severe dermatitis in AD patients." (PMID 33670758, 2021). "These cells, when activated, release pro-inflammatory cytokines, including IL-4, IL-13, and IL-31 which led to the dermatitis." (PMID 34948125, 2021). "Accumulating evidence underscores the notion that AD can be re-defined as a form of skin inflammation attributable to excessive IL-13/(IL-4) signaling in individuals with atopic diathesis." (PMID 33233866, 2020). "It acts via a heterodimeric receptor composed of IL-31Rα and oncostatin M receptor β and expression of IL-31 correlates with the expression of IL-4 and IL-13 suggesting that IL-31 is involved in Th2-mediated skin inflammation." (PMID 25756056, 2015). "Moreover, the expression levels of inflammatory cytokines IL-4 and IL-13, as well as dermatitis scores, significantly improved after UFB shower treatment in Dfb-induced AD mice." (PMID 39790997, 2024). "The pathogenesis of dermatitis involves epidermal barriers abnormalities, leading to heterogeneous immunological dysregulations predominantly in type 2 immunity (Th2, IL-4, IL-13, IL-31), but also including varying degrees of upregulation of the Th1 (IFN-γ), Th17 (IL-17), and Th22 axes (IL-22)." (PMID 38550585, 2024).
dermatitis (continued). "The mediators involved in Th2 reactions include IL-4, IL-5, IL-13, IL-33, and IgE, in which IL-4 triggers dermatitis, similar to its effect in AD by inhibiting the production of IFN-gamma, thereby inducing an immune imbalance and increasing the synthesis of IgE." (PMID 36077570, 2022). "AD is a pruritic skin disorder with barrier dysfunction and elevated expression of IL-4 and IL-13." (PMID 35563259, 2022). "Recent transcriptomic analyses have revealed that in AD, gene expression levels of IL-13 correlate more with the intensity of skin inflammation than those of IL-4, suggesting that the IL-13-producing dermal ILC2s may be more involved in the pathogenesis of AD." (PMID 33233866, 2020). "The pathogenic importance of IL-4/IL-13 signaling in AD has been recently highlighted because its blockage by dupilumab, a specific anti-IL-4 receptor α (IL-4Rα, IL4R) antibody, successfully improves skin inflammation in patients with AD." (PMID 31284553, 2019). "To address the question whether GMP administration might modulate this Th2 inflammatory response in dermatitis, we examined mRNA changes of IL-4, IL-5, and IL-13 by qRT-PCR in injured skin tissue." (PMID 28265582, 2017). "Interestingly, GMP administration before AD-induction decreased in 83.56, 96.5, and 88.38% the expression of IL-4, IL-5, and IL-13 in dermatitis skin." (PMID 28265582, 2017). "Our results indicated that 7,8,4′-THIF, a metabolite of the soy isoflavone daidzin, suppresses the development of DNCB-induced dermatitis in NC/Nga mice, probably by down-regulating various Th2- (TARC, IL-4, IL-5, and IL-13) and Th1-associated factors (IL-12 and IFN-γ)." (PMID 25170825, 2014). "In our study, we found that HB markedly suppressed mRNA expression of IL-4, IL-13, and the transcription factor GATA3 known to drive immune cells to produce a type 2 immune response in dermatitis skin tissue." (PMID 34531749, 2021). "Ethanol extracts of Ampelopsis brevipedunculata rhizomes inhibited an AD-like skin inflammation through downregulation of serum IgE levels and expression of TNF-α, interferon (IFN)-γ, IL-4, IL-13, and IL-31 in a BALB/c AD model." (PMID 33335525, 2020). "Collectively, our study indicates that bathing with HMW ameliorates DNCB-induced skin inflammation by inhibiting the allergic response (such as serum IgE level and scratching behavior), inflammatory response (such as inflammatory cytokines; IL-1β, TNF-α, and IL-13) in female skh-1 hairless mice." (PMID 29029618, 2017).
food allergy (47 papers, 2010 to 2025). Gastrointestinal disturbances, skin eruptions, or shock due to allergic reactions to allergens in food. "The gene–environment interactions we identified reveal a triad of Th2-sensitizing genotypes—IL4R rs1801275 AA, IL-4 rs2243250 CC, and IL13 rs20541 GG—that confer 4- to 26-fold elevated food allergy risk under vitamin D deficiency." (PMID 40927566, 2025). "Genetic susceptibility in Th2 pathway genes (IL4R, IL-4, IL13) dramatically amplified food allergy risk under vitamin D deficiency, with AA/GG/CC genotypes conferring 4- to 26-fold increased susceptibility." (PMID 40927566, 2025). "These interactions demonstrate that genetic susceptibility in Th2 pathway genes (IL4R, IL-4, IL13) dramatically amplifies food allergy risk under vitamin D deficiency, while MS4A2 variants modulate vitamin D’s protective effects." (PMID 40927566, 2025). "It has been appreciated for many years that food allergy was associated with an allergen-specific type 2 cytokine profile, defined by production of IL-4, IL-5, and IL-13 from CD4+ T cells." (PMID 36880703, 2023). "IL-4, and IL-13 are associated with humoral responses, and are drivers of inflammation in atopy and food allergies." (PMID 36830973, 2023). "CITRUS did not detect expression of the Th2 cell cytokines IL-5, IL-10, or IL-13, cytokines that are strongly associated with food allergy." (PMID 32698761, 2020). "Children fed colostrum with detectable levels of IL13 in colostrum were found to be less likely OR 0.1 (95% CI 0.01–0.83) associated with parental-reported food allergy at the age of 6 months." (PMID 28538696, 2017). "IL13 has been shown to not only drive goblet cell hyperplasia, but also increase allergen delivery across the intestinal epithelium by the formation of GAPs and secretory cell associated passages (SAPs), and been implemented in promoting oral allergen sensitization and food allergy pathogenesis." (PMID 33613522, 2020). "Detectable IL13 in mature milk reduced the risk of parent-reported eczematous rash development, whilst detectability of this cytokine in colostrum seems to have a similar association with food allergy/sensitivity/intolerance reported by the mothers at six months of age." (PMID 28538696, 2017). "The key cytokines in food allergy—interleukin‐4 (IL‐4), IL‐5, and IL‐13—operate in peripheral tissues upon inflammatory stimuli." (PMID 40730516, 2025). "Conversely, treatment with BDMC in a mouse model of food allergy reduced serum levels of the Th2 cytokines IL-4, IL-5, and IL-13 by less than 30%, while increasing IFN-γ levels." (PMID 37998337, 2023). "In IgE-mediated food allergies, IL-4 and IL-13 can promote allergen-specific immunoglobulin E (IgE) antibody production and intestinal allergic inflammation." (PMID 35769569, 2022). "This gene is known to be expressed by epithelial cells and involved in IL-13-induced transcriptional changes in bronchial epithelial cells, suggesting a possible role for epithelial SERPINB10 in mediating susceptibility to food allergy." (PMID 33365031, 2020). "In the context of established food allergy IL-13 can act to dramatically increase the number of these small intestinal GAPs, and expand the type of secretory cells that form these passages to include Paneth cells and EECs." (PMID 33365031, 2020). "Severe infiltration of CD4+ T cells and over production of the Th2 cytokines, including IL-4, IL-5 and IL-13 have been documented in the intestinal mucosa of humans and mouse models of GI food allergy." (PMID 31164117, 2019). "Parental-reported food allergy was reported less often when IL13 was detectable in colostrum OR 0.10 (95% CI 0.01–0.83)." (PMID 28538696, 2017). "Increased TGFβ2 levels in HM are associated with a higher incidence of reported eczema, with detectable IL13 in colostrum showing protective effects for food allergy and sensitization." (PMID 28538696, 2017).
food allergy (continued). "The Th2-related cytokines IL-4, IL-5, and IL-13 were increased in mLNs from food allergy-induced mice." (PMID 27445434, 2016). "These effector cells, through exposure to an array of Th2 cytokines (IL-4, IL-5, IL-9, IL-13, IL-15 and IL-18) in the intestinal immune system, are primed for food allergy or anaphylactic reactions upon subsequent antigen exposure." (PMID 27840774, 2015). "These effector cells then release a collection of Th2 cytokines (IL-4, IL-5, IL-9, IL-13, IL-15 and IL-18) that are organized in the intestinal immune system for prompting food allergy or anaphylactic immune responses upon successive exposure to the antigen." (PMID 27840774, 2015). "Furthermore, it has been found that chitosan oligosaccharides protect against shrimp protomyosin‐induced food allergy by downregulating IL‐4, IL‐5, and IL‐13 and upregulating interferon (IFN)‐γ." (PMID 40901656, 2025). "Interleukin 3 (IL-3), interleukin 5 (IL-5), and interleukin 13 (IL-13) were cytokines produced in a statistically significant way by peripheral blood mononuclear cells stimulated in vitro with cow’s milk in patients with food allergies." (PMID 37763228, 2023). "Since it has not been clearly defined which segment of the intestine is involved in food allergy-induced type 2 immune responses, we investigated the gene expressions of IL-4, IL-5, and IL-13 in the duodenum, jejunum, ileum, and colon by using quantitative PCR." (PMID 36501013, 2022). "Individuals with food allergies typically develop Type 2 responses to the allergen, including the production of a number of pro-inflammatory cytokines that drive allergic responses, such as interleukin (IL)-4, IL-5, IL-9, and IL-13 from Th2 and ILC2 cells." (PMID 35769569, 2022). "The short‐ and long‐term impact of IL‐4/IL‐13 blockade remain unclear in the context of established food allergy." (PMID 34429871, 2021). "The reduction in ILC2s in the mice that received the NE vaccines may also be a critical factor for the observed reduction in allergic reactivity, as IL-4 and IL-13 producing ILC2s have also been shown to promote experimental food allergy." (PMID 33717078, 2021). "Recent studies provided evidence that IL-4/IL-13 pathways play an important role in food allergy." (PMID 29051540, 2017). "Thus, the therapeutic inhibition of IL-4/IL-13 signaling with dupilumab is expected to lead to a reduction in the recruitment of intestinal mast cells with consequent attenuation of the clinical expression related to food allergy." (PMID 39203933, 2024). "IL-13 increases were associated with EoE subjects with concomitant food allergies (data not shown)." (PMID 20815913, 2010). "The carotene lycopene reduced the cytokine expression of IL-4, IL-13, and IL-9 by about 60% in an ovalbumin (OVA)-induced food allergy model." (PMID 37998337, 2023). "Abrocitinib, an inhibitor of JAK1 that is part of the signaling complex downstream of a number of cytokine receptors including IL-4, IL-13, IL-9, and TSLP, is also in a phase I trial for the treatment of food allergy (NCT05069831)." (PMID 36880703, 2023). "As a result, we observed that dietary emulsifiers, especially P80, significantly exacerbated food allergy symptoms, with increased OVA-specific IgE induction and accelerated type 2 cytokine expressions, such as IL-4, IL-5, and IL-13, in the colon." (PMID 36501013, 2022). "Oral administration of DON together with whey protein facilitated food allergy induction, indicated by increased ASR values and serum levels of whey-specific IgE, and the production of IL-5 and IL-13 in re-stimulated splenocytes." (PMID 34975906, 2021). "Dupilumab was the first FDA-approved biologic for eosinophilic esophagitis, and in combination with omalizumab, it has been investigated for blocking both IgE and IL-4/IL-13 and is also being investigated as both monotherapy and as an adjunct with OIT for food allergy." (PMID 40004029, 2025).